KRAS (KRas proto-oncogene, GTPase)
Diseases named in the same sentence as KRAS in open-access papers (continued):
Sharing a sentence is not in itself a finding about the gene and the disease.
mucinous tumors (continued). "Only 2/3 mucinous tumours with concomitantly sampled fallopian tubes harboured KRAS mutations." (PMID 23800114, 2013). "The low prevalence of KRAS mutations in our BAN MSS samples may be correlated to the high percentage of mucinous tumour observed (30% in BAN MSS samples with wildtype KRAS)." (PMID 23286373, 2013). "Notably, when KRAS codon 12-mutated tumours were compared with tumours being either KRAS wild-type or codon 13-mutated, there was a significantly higher proportion of mucinous tumours in the former category (p = 0.032 and p = 0.024)." (PMID 24020794, 2013). "Another interesting observation was KRAS, a gene reported to be mutated in mucinous tumors." (PMID 23078675, 2012). "Notably, type I tumors evolve slowly and are associated with distinct molecular changes that are rarely found in type II tumors, such as BRAF and KRAS mutations for serous tumors, KRAS mutations for mucinous tumors, CTNNB1 and PTEN mutations for endometrioid tumors." (PMID 33912469, 2021). "KRAS and GNAS mutations, which are frequently observed in pancreatic and appendix mucinous neoplasms, have been documented to be positive in some cases of PRMC." (PMID 41002570, 2025). "Another report generated the relationship between benign, borderline, invasive low-grade and high-grade mucinous tumors and found that either a KRAS or CDKN2A event leads to the initiation of benign tumors." (PMID 37185420, 2023). "Like MOTs, colorectal mucinous carcinomas are the only group in which frequent KRAS and BRAF mutations are found; mutations in both genes are absent in breast and rare gastric mucinous carcinomas, and appendiceal mucinous tumors are BRAF wild type." (PMID 26257827, 2015). "Among mucinous tumors, the most prevalent mutations occur in the mitogen activated protein kinase (MAPK) pathway, including KRAS mutations and ERBB2 amplification/overexpression." (PMID 25986173, 2015). "Mucinous tumors are driven by KRAS or ERBB2 amplification, representing about 3% of ovarian tumors." (PMID 38352443, 2024). "KRAS and BRAF mutations are mutually exclusive in CRC: the shortage of BRAF mutations detected in appendiceal neoplasms with PMP seems to be a consistent consequent high prevalence of KRAS mutations among appendiceal mucinous neoplasms." (PMID 33712927, 2021). "Although this could indicate tumor progression of the peritoneal metastasis, the presence of both KRAS and GNAS mutations in particular point towards peritoneal metastasis of a primary mucinous tumor of the appendix or pancreas." (PMID 32711552, 2020). "Activating KRAS mutations are more common in mucinous tumours than in all other histological types 17, 34, while no mucinous tumours have been found to harbour a BRAF mutation." (PMID 26800494, 2016). "Compared with conventional adenocarcinomas, mucinous tumors tend to be associated with young age, advanced tumor stage, and distinct molecular patterns, such as microsatellite instability and mutations of the BRAF and KRAS genes." (PMID 26081940, 2015). "Age, gender, synchronous or metachronous metastases, preoperative laparotomy or laparoscopy, PCI ≥ 20, TN-stage, primary tumour location, mucinous tumors, grade of differentiation, and the presence of KRAS or BRAF mutations were also analyzed but none was significantly associated with lead time." (PMID 36117176, 2022). "In the multivariate regression model for clinical characteristics KRAS mutations were associated with an increased incidence of lung and bone metastases and decreased incidence of adrenal metastases; PIK3CA mutations were marginally correlated with mucinous tumors (p = 0.05)." (PMID 22675430, 2012).
mucinous tumors (continued). "In mucinous tumors where KRAS mutation is common, the gene was not significantly altered." (PMID 23078675, 2012). "KRAS, BRAF and SACT prior to HIPEC; HIPEC chemotherapy type (oxaliplatin or mitomycin); poor and/or mucinous tumour differentiation; and the presence of signet cells in tumour did not significantly predict OS (p > 0.05)." (PMID 36400886, 2023). "Additionally, there were no observed mutations in other histological EC tumours such as serous, clear cell, or mucinous tumour types arguing that KRAS mutations may not have metastatic potential." (PMID 35269800, 2022). "Here, we report the effectiveness of combinatorial targeting of two KRAS-mediated parallel pathways in reducing MUC2 production and mucinous tumor growth in vitro and in vivo." (PMID 28640835, 2017). "Only six lesions were classified as non-mucinous; however, two of them showed mutations in KRAS and GNAS, recategorizing these lesions as mucinous neoplasms, which led to a modification of the follow-up plan." (PMID 41464573, 2025). "Importantly, we demonstrated promising preclinical data of mucinous tumor growth suppression in ex vivo colonoid cultures and in vivo IP PDX models derived from KRAS mutant colon/appendix cancers." (PMID 31958897, 2020). "Unlike mucinous tumors, high grade serous tumors typically do not express BRAF and KRAS mutations." (PMID 33946684, 2021).
serous ovarian cancer (52 papers, 2008 to 2026). "KRAS mutations are associated with low-grade serous ovarian cancer, often predicting poor prognosis, particularly in patients with poor chemotherapy response." (PMID 39680618, 2024). "A patient-derived cell line from a low-grade serous ovarian cancer with a KRAS mutation was engrafted in zebrafish embryos." (PMID 38791891, 2024). "Activating KRAS mutations are found in more than 20% of all human cancers, including low-grade serous ovarian carcinoma, lung carcinoma, pancreatic cancer, endometrial cancer, and colorectal carcinoma." (PMID 33244099, 2020). "In ovary serous carcinoma, patients with KRAS G12 V mutation had poor survival than those with KRAS G12D mutation or KRAS wild type." (PMID 30419860, 2018). "Typically, low-grade serous ovarian carcinoma has few somatic mutations, which are mainly found in genes associated with the mitogen-activated protein kinase pathway such as KRAS, BRAF and NRAS." (PMID 29132324, 2017). "BRAF is the downstream effector of KRAS, which was reported to be common mutation (28–35 %) in serous borderline (SB)/low grade serous ovarian cancer (LGS-OvCa)." (PMID 26490766, 2015). "LGS-OvCa harboring KRAS mutation is a chemoresistant disease that accounts for 10 % of serous ovarian cancer." (PMID 26490766, 2015). "Furthermore, KRAS mutations are more common in low-grade serous ovarian cancer along with BRAF mutations." (PMID 38730733, 2024). "The frequency of KRAS/BRAF mutations associated with low-grade serous ovarian carcinoma (LGSC)/serous borderline tumors (SBTs) in Japan is unknown." (PMID 31892193, 2019). "Low-grade serous ovarian cancers typically have either BRAF or KRAS mutation." (PMID 30018258, 2018). "In KRAS-amplified Kuramochi cells (representing high-grade serous ovarian carcinoma), BI2865 enhanced paclitaxel efficacy, despite greater baseline chemoresistance." (PMID 41683990, 2026). "KRAS gene mutations are commonly found in LGSOC but not in high-grade serous ovarian carcinoma (HGSOC)." (PMID 35692807, 2022). "Notably, two responders in the dose escalation cohort had mutations in the MAPK or PI3K pathways, including one with KRAS-mutant CRC with neuroendocrine features and another with dual KRAS/PIK3CA-mutant low grade serous ovarian cancer." (PMID 30425349, 2018). "Furthermore, transcriptome analysis confirmed the typical KRAS mutation (rs121913529; HGVS nomenclatures: NM_004985.4:c.35G > T, NP_004976.2:p.Gly12Val) frequently observed in low-grade serous ovarian carcinomas." (PMID 29132324, 2017).
serous ovarian cancer (continued). "The absence of KRAS/BRAF mutation also distinguishes BIN-67 from low-grade ovarian serous carcinomas and mucinous cancers." (PMID 23433318, 2013). "In ovarian serous cancers, KRAS is mutated in predominantly in low-grade but not in high-grade serous cancers." (PMID 23554638, 2010). "Notably, KRAS and BRAF mutations in serous borderline tumor or low-grade ovarian serous carcinoma are generally mutually exclusive." (PMID 23554638, 2010). "In low-grade serous ovarian carcinoma the mitogen-activated protein kinase (MAPK) pathway is activated, a kinase cascade that mediates the transmission of growth signals into the nucleus, via mutations in KRAS and BRAF, the upstream regulators of the MAPK pathway." (PMID 33043759, 2020). "Responses were seen in tumours harbouring BRAF fusions, GNA11, GNAQ, KRAS, NF1, and NRAS alterations, most frequently in low-grade serous ovarian cancer, central nervous system tumours, and uveal melanoma." (PMID 41664938, 2026). "This point also provides a rationale for exploring MAPK kinase (MEK) inhibitors in the treatment of low-grade serous ovarian cancer, such as selumetinib, trametinib or dabrafenib, which are MEK1 and MEK2 inhibitors (MEKi) that indirectly inhibit the BRAF and KRAS pathways." (PMID 32679669, 2020).
chronic pancreatitis (50 papers, 2002 to 2025). A chronic inflammatory process causing damage and fibrosis of the pancreatic parenchyma. "The uncertainty regarding the potential presence of KRAS mutations in benign conditions such as chronic pancreatitis should also be highlighted." (PMID 31323810, 2019). "One study identified circulating DNA with KRAS mutations in up to 20% of chronic pancreatitis patients." (PMID 31412682, 2019). "A study combining the detection of ctDNA KRAS mutations with CA 19-9 levels differentiated PDAC (47 patients) from chronic pancreatitis (31 patients) with a sensitivity of up to 98% and a specificity of 77%." (PMID 31412682, 2019). "By using Ion Torrent NGS technology, KRAS mutations have been reported in plasma of 3.7% of healthy controls and 4.3% of patients with chronic pancreatitis." (PMID 28199989, 2017). "We also detected KRAS cfDNA mutations in 3.7% (N=14) of healthy controls and in 4.3% (N=6) of subjects with chronic pancreatitis, but at significantly lower allelic fractions than in cases." (PMID 27705932, 2016). "Based on the combination of histo/cytopathological and KRAS mutation analysis, a medical or surgical conservative treatment is pertinent for patients with pancreatic solid mass suggestive of pseudo-tumorous chronic pancreatitis." (PMID 24212643, 2011). "Importantly, mutations of KRAS are often found in early neoplastic lesions resulting from chronic pancreatitis." (PMID 36835366, 2023). "In addition, while limited in sample size, two studies described circulating KRAS mutations in 5% (2/37) and 13% (4/31) of patients with chronic pancreatitis." (PMID 27705932, 2016). "In fact, it has been suggested that it is possible to detect KRAS mutations in 7.4% of exoDNA and 14.8% of cfDNA in healthy controls, and in 20% of patients with chronic pancreatitis, and these numbers may increase as the sensitivity of the technique increases." (PMID 33924143, 2021). "In fact, the MAF of KRAS in ctDNA is different in patients with pancreatic cysts, chronic pancreatitis, benign tumors, localized, locally advanced and metastatic PDAC." (PMID 33924143, 2021). "They examined KRAS codon 12 mutations in cfDNA from serum in 47 patients with histologically proven PDAC and 31 controls with chronic pancreatitis using PCR and allele-specific amplification." (PMID 33671729, 2021). "Our results highlighted that the diagnostic accuracy of KRAS mutation for PDAC was of variable sensitivity and specificity when compared with PanINs and chronic pancreatitis, but had a higher specificity among healthy individuals." (PMID 32825312, 2020). "By adding KRAS mutation analysis, the diagnosis changed correctly in nine cases: eight patients with PDAC and one patient with chronic pancreatitis." (PMID 28969083, 2017). "Targeted next generation sequencing (tNGS) analysis of mutation hotspots in 50 cancer genes was conducted in 26 patients with PDAC, 14 patients with chronic pancreatitis (CP) and 12 healthy controls with KRAS status validated by digital droplet PCR." (PMID 29152076, 2017). "In our series, we detected 3.7% (N=14) KRAS positive individuals in the healthy controls (N=9 at hotspot codons) and 4.3% (N=6) in subjects with chronic pancreatitis, three of them at PDAC hotspot codon with an allelic fraction >1%." (PMID 27705932, 2016). "Among the most common genetic alterations contributing to pancreatic carcinogenesis, oncogenic mutations in KRAS are the most frequently detected not only in frank PDAC but also in its best characterized preneoplastic disease, namely chronic pancreatitis." (PMID 27415425, 2016). "β-catenin is stabilized in response to caerulein induced chronic pancreatitis but is turned off simultaneously to the induction of KRAS mediated ADM." (PMID 24212973, 2011). "Chronic pancreatitis has been directly linked to the development of PanINs and PDAC in a KRAS-driven GEMM." (PMID 24212973, 2011).
chronic pancreatitis (continued). "A meta-analysis showed that the frequency of KRAS mutations in PanIN lesions increased with the lesion grade in PDAC patients, while in those with chronic pancreatitis, the proportion of KRAS-harboring PanIN lesions was relatively low and independent of their grade." (PMID 39839479, 2024). "KRAS measurements obtained through the last of these approaches appear to be highly unspecific, since levels of KRAS in pancreatic juice are also increased in chronic pancreatitis and other inflammatory diseases." (PMID 39594780, 2024). "On the other hand, the KRAS mutation is an important hallmark that helps rule out chronic pancreatitis." (PMID 37760400, 2023). "Thus, for example, the combination of KRAS mutations and CA19.9 showed a sensitivity of 0.98 and a specificity of 0.77 to differentiate PDAC from chronic pancreatitis." (PMID 33924143, 2021). "We also detected at least one KRAS mutations at PDAC hotspot codons in the plasma of 4/132 (3.0%) patients with chronic pancreatitis and of 9/374 (2.4%) healthy controls whereas none were detected in those subjects of the pilot series." (PMID 27705932, 2016). "In agreement with previous reports, we also demonstrated that the proportion of cases with detectable cfDNA KRAS mutations tended to increase with more advanced stages and that KRAS allelic fractions were higher in cases than controls or in patients with chronic pancreatitis." (PMID 27705932, 2016). "But, some chronic pancreatitis patients with KRAS mutations never develop PDAC." (PMID 35147102, 2022). "Indeed, KRAS mutations can be detected in plasma in some non-cancerous diseases such as chronic pancreatitis." (PMID 34638228, 2021). "Moreover, KRAS mutations have also been isolated in non-tumoral samples (i.e., chronic pancreatitis) and more surprisingly in three of 114 (2.6%) healthy subject samples." (PMID 32974169, 2020). "Several studies have not detected KRAS mutations in the ctDNA patients with chronic pancreatitis." (PMID 31323810, 2019). "In fact, the presence of more than one KRAS mutation in each pancreatic juice sample has been reported from older healthy individuals and patients with pancreatic non-malignant abnormalities such as chronic pancreatitis and cysts." (PMID 30611220, 2019). "However, while less than 1% of KRAS mutations reported in ICGC/COSMIC data are located at other codons, 13% (13/97), 22% (2/9), and 31% (6/19) of such mutations were detected in the plasma samples of cancer cases, chronic pancreatitis, and controls, respectively." (PMID 27705932, 2016). "KRAS mutations were found in 22 patients with PDAC (47%) and in 4 controls with chronic pancreatitis (13 %), none of whom developed a PDAC within the 36 months of follow-up." (PMID 33671729, 2021).